MERTK (MER proto-oncogene, tyrosine kinase)
Diseases named in the same sentence as MERTK in open-access papers (continued):
Sharing a sentence is not in itself a finding about the gene and the disease.
gastric cancer (9 papers, 2016 to 2025). A primary or metastatic malignant neoplasm involving the stomach. "Comparable to our results MERTK overexpression was associated with higher tumor stages in gastric cancer, but in gastric cancer patients high MERTK expression was also associated with shorter overall survival." (PMID 27081701, 2016). "According to recent research, it was shown that 8.3% (16 out of 192) of patients diagnosed with gastric cancer had a significantly elevated level of total MERTK protein expression." (PMID 41166341, 2025). "Gastric cancer (GC) has significant heterogeneity, and there is evidence of increased expression of MERTK in gastric cancer." (PMID 41166341, 2025). "Subsequent multivariate Cox regression analysis showed that high MerTK expression was an independent OS factor for gastric cancer (HR = 2.250, 95% CI = 1.301–3.891, p < 0.05)." (PMID 38545840, 2024). "CRISPR/Cas9 knockout and siRNA knockdown of MerTK in the gastric cancer cell lines SNU1, SNU5, and MKN45 was used to analyze protein expression, growth, migration, and invasion properties in vitro and in a murine xenograft model." (PMID 38545840, 2024). "Collectively, RXDX-106 shows an anti-proliferative effect through inhibiting proliferative signals and activating apoptotic singals in MerTK activated gastric cancer PDCs." (PMID 29285287, 2017). "MER tyrosine kinase (MerTK) is expressed in a variety of malignancies, including gastric cancer (GC)." (PMID 29285287, 2017). "In gastric cancer UNC1062 treatment decreased proliferation only in MERTK positive cells accompanied by a decrease in ERK phosphorylation." (PMID 27081701, 2016). "MERTK has been reported to be overexpressed in multiple cancers along with gastric cancer." (PMID 35646067, 2022). "To explore the role of MerTK in gastric adenocarcinoma (GAC), we analyzed the expression of MerTK and other TAMR family members Axl and Tyro3 in a panel of gastric cancer cell lines (MKN45, SNU1, SNU5, KATO‐III, NCI‐N87, and AGS)." (PMID 38545840, 2024). "Furthermore, findings demonstrated a significant inhibition of MERTK-overexpressing GC cells following MERTK knockdown, indicating MERTK might be a possible novel therapeutic target in the treatment of gastric cancer." (PMID 41166341, 2025). "The role of MerTK has not been assessed in gastric cancer (GC)." (PMID 29228560, 2017).
retinal disease (9 papers, 2010 to 2023). "Altogether, our data well justify future studies toward simple and safe therapy for retinal disease due to MerTK deficiency, combining anti-inflammatory with ROCK inhibitor therapies possibly as eye drop formulations for safe, local, non-invasive therapy." (PMID 34440696, 2021). "MERTK was originally associated with retinal disease beginning in the first decade of life, and most subsequent studies describe similar ages at onset." (PMID 26656104, 2015). "To date, six families have been reported with retinal disease due to MERTK mutations." (PMID 20300561, 2010). "The region contains 102 genes of which anaphase promoting complex subunit 1 (ANAPC1), c-mer proto-oncogene tyrosine kinase (MERTK) and nephronophthisis 1 (NPHP1) have been previously associated with retinal disease or retinal function." (PMID 25517981, 2014). "Despite these uncertainties, the identification of the genetic defect underlying this naturally occurring canine overexpression model for MERTK is a novel and exciting finding and could therefore inform future studies of MERTK in both human and canine retinal disease." (PMID 28813472, 2017).
Stroke (9 papers, 2021 to 2025). Sudden impairment of blood flow to a part of the brain due to occlusion or rupture of an artery to the brain. "First utilizing the tMCAO model of IS, we showed that eCIRP is released into CSF and microglial MerTK expression is decreased in vivo 24 h post-stroke." (PMID 40766256, 2025). "A recent study revealed that MEGF10 and MERTK were expressed on the membranes of microglia/macrophages and astrocytes in mice with ischemic and hemorrhagic stroke and that MEGF10 and MERTK levels were significantly increased 14 days after stroke." (PMID 38727249, 2024). "Inducible ablation of astrocytic MEGF10 or MERTK reduces synaptic engulfment in the peri-infarct region and increases the number of dendritic spines 14 days after stroke, which also promotes enhanced functional recovery." (PMID 39086680, 2023). "Mice lacking the phagocytic receptor Mer receptor tyrosine kinase (MerTK) showed improved neuronal survival and stroke outcome." (PMID 36219377, 2023). "Blocking the phagocytic receptors MerTK and the vitronectin receptors (integrins αvβ3 or αvβ5) can also prevent the phagocytosis of stressed neurons in stroke models." (PMID 34948237, 2021). "MEGF10 and MERTK protein level was notably increased at 14 day following stroke." (PMID 34836962, 2021). "For instance, M1-MG may exhibit excessive phagocytosis, also called phagoptosis, eliminating viable neurons and live synapses through multiple epidermal growth factor-like domains protein 10 (MEGF10) and tyrosine-protein kinase Mer (MERTK) in the post-stroke repair and remodeling stage." (PMID 35518646, 2022). "In response to stroke, reactive astrocytes engulf synapses through MEGF10, MERTK and GULP1-related pathways." (PMID 39086680, 2023). "We found that compared with the corresponding sham group, 14 days after stroke, MEGF10 and MERTK expression was significantly increased." (PMID 34836962, 2021). "We did not detect any abnormal behavior of mice that lacked MEGF10 or MERTK, at least within 14 days after stroke, suggesting the different mechanisms of de novo synapse formation in the developing brain and synapse remodeling after injury." (PMID 34836962, 2021). "By analyzing TUNEL+ apoptotic cells, we found that a lack of MEGF10 and MERTK did not affect cell death after stroke." (PMID 34836962, 2021). "To determine whether MEGF10 and MERTK pathways mediate synapse engulfment after stroke, we investigated the expression and localization of MEGF10 and MERTK at different time points after stroke." (PMID 34836962, 2021). "We found that Mac-2 was upregulated as early as 1 day following stroke, but without changes of MEGF10 and MERTK protein levels." (PMID 34836962, 2021).
viral infection (9 papers, 2018 to 2023). "We then decided to focus principally on studying circMerTK because its expression was highly induced by viral infection in vivo and it is derived from the pre-mRNA of MerTK, a crucial gene that has been previously implicated in innate immunity." (PMID 36847523, 2023). "MERTK has also been implicated in maintenance of the blood brain barrier during viral infection." (PMID 31805065, 2019). "Furthermore, it is thought that MerTK is an antiviral innate immunity factor that synergistically dampens innate immune responses, favoring virus propagation, and it has been implicated in innate tolerance regulation after viral infection." (PMID 36847523, 2023). "In vivo and in vitro studies have established that linear MerTK can modulate innate immunity against various viral infections." (PMID 36847523, 2023). "In our study, THP-1 cells expressing the synthetic receptor with the MERTK cytoplasmic domain were relatively resistant to virus infection but induced notable virion clearance." (PMID 34367135, 2021). "Using Mertk-/- mice, Miner and colleagues show that MERTK maintains the blood-brain barrier during viral infection with either West Nile or La Crosse encephalitis viruses." (PMID 31805065, 2019). "Since MerTK is known as a regulator of innate immunity against viral infection, we sought to determine whether circMerTK derived from the pre-mRNA of MerTK possessed an immune function in response to IAV infection." (PMID 36847523, 2023). "Nonetheless, little is known about the role of MERTK in viral infections." (PMID 36851782, 2023). "Although research in this area has mainly focused on the role of MerTK in macrophages, it should also be noted that brain microvascular ECs have been shown to express MerTK,116 and that it is required for tightening the blood–brain barrier during viral infection." (PMID 30980657, 2019). "Our results indicate that this is facilitated during viral infection by an upregulation of the TAM receptor, Axl, which cooperates with the main apoptotic cell sensor in human macrophages, MerTK, in maintaining their efferocytic capacity." (PMID 29400409, 2018). "After virus entry, MERTK suppresses mRNA expression of IFN-β and promotes viral infection." (PMID 36851782, 2023). "However, the involvement of MERTK, another member of the TAM receptors, in viral infection remains unknown." (PMID 32172658, 2020).
diabetes (8 papers, 2016 to 2025). "Results revealed that exogenous aPC treatment prevented the diabetes-induced reduction in macrophages efferocytosis and that aPC’s effect was lost in diabetic ApoE−/− mice treated with MerTK specific morpholino." (PMID 41083981, 2025). "For example in the NOD (non-obese diabetic) mouse model of spontaneous diabetes, knockdown of MERTK results in resistance to the development of diabetes, and this effect appears to be mediated by bone-marrow derived dendritic cells." (PMID 26990204, 2016). "Moreover, studies have confirmed that significant alterations in AGT and MERTK are common genes that promote diabetes and AD." (PMID 39840062, 2024). "In summary, we describe a novel cellular pathway involved in diabetic efferocytosis, wherein diabetes-induced decrease in miR-126 expression results in upregulation of ADAM9 expression that in-turn leads proteolytic cleavage of MerTK and formation of inactive sMer." (PMID 27827458, 2016). "Furthermore, our proteomic results revealed a significant reduction in the levels of MERTK (beyond the insulin receptor) and IGFBP1, leading to decreased insulin sensitivity and triggering IR and diabetes." (PMID 39840062, 2024). "Previous studies have also linked apoptotic cells with inhibition of DC maturation and activation via the NF-κB pathway, a process found to be dependent on MERTK activation of the PI3K/AKT pathway in a non-obese diabetes mouse model." (PMID 37958886, 2023). "In the present study, we demonstrate that diabetes-mediated decrease in miR-126 leads to a corresponding increase in its target, ADAM9, which in turn cleaves MERTK (inactivates downstream engulfment signaling), thus resulting in defective macrophage efferocytosis of apoptotic cardiomyocyte." (PMID 27827458, 2016). "In contrast to TAM receptor expression in microglial cells, both MerTK and AXL showed a relatively high level of expression in the cortical astrocytes and Muller glia of the retina that was not significantly altered by diabetes, consistent with their role as non-professional phagocytes." (PMID 40940761, 2025).
hepatocellular carcinoma (8 papers, 2018 to 2025). A malignant tumor that arises from hepatocytes. "Although it is reported that MERTK polymorphisms affect the severity of viral and metabolic liver diseases, being able to influence fibrosis progression and hepatocellular carcinoma development, the mechanisms remain unknown." (PMID 36003399, 2022). "MerTK drives anti-PD-1/PD-L1 resistance in hepatocellular carcinoma by limiting ferroptosis and promoting an immunosuppressive microenvironment, with its inhibition by sitravatinib enhancing therapy efficacy." (PMID 39315094, 2024). "MERTK N-glycosylation was also found to be critical for its homodimerisation, stability and tumour-promoting effect in hepatocellular carcinoma." (PMID 37958886, 2023). "N-glycosylation of Asn294 and Asn454 of Mer tyrosine kinase (MerTK) promotes the proliferation of hepatocellular carcinoma (HCC) by stabilizing the expression of MerTK." (PMID 37894512, 2023). "CircMerTK, on the other hand, is a circular RNA derived from MerTK pre-mRNA, and has been demonstrated to be significantly downregulated in hepatocellular carcinoma (HCC) tissues and identified as a potential new diagnostic biomarker for HCC." (PMID 36847523, 2023).
pulmonary fibrosis (8 papers, 2022 to 2025). Chronic progressive interstitial lung disorder characterized by the replacement of the lung tissue by connective tissue, leading to progressive dyspnea, respiratory failure, or right heart failure. "Importantly, nintedanib downregulated critical profibrotic mediators including TGF-β1 and Mer tyrosine kinase (MerTK)—a receptor implicated in pulmonary fibrosis pathogenesis." (PMID 40650314, 2025). "Recently, an elevated MerTK expression was found in lung macrophages of patients affected by idiopathic pulmonary fibrosis (IPF) and from mice with bleomycin-induced pulmonary fibrosis." (PMID 38509595, 2024). "In pulmonary fibrosis, this negative regulation is defective, and MERTK mainly exhibits profibrotic effects." (PMID 37120511, 2023). "This IM subtype seems to be consistent with previously reported SPP1/MERTK-expressing macrophages in idiopathic pulmonary fibrosis." (PMID 35820705, 2022). "However, in pulmonary fibrosis, although MERTK expression is increased, mitochondrial membrane potential and efferocytosis function are not enhanced, leading to defective negative regulation." (PMID 37120511, 2023). "As lung fibroblasts are major effector cells in pulmonary fibrosis, we also explored whether MERTK-overexpressing macrophages promote the activation of and collagen secretion by lung fibroblasts." (PMID 37120511, 2023). "However, depending on the research interest, myeloid cell markers such as CD64 could be exchanged with Siglec F and MerTK, especially for lung fibrosis or macrophage phagocytosis studies." (PMID 39481389, 2024). "Interestingly, in pulmonary fibrosis, the negative regulation by macrophage efferocytosis is defective, and MerTK mainly exhibits profibrotic effects, suggesting that targeting MerTK in macrophages may help to attenuate pulmonary fibrosis." (PMID 38509595, 2024). "Our study reveals a previously unsuspected profibrotic effect of elevated macrophage MERTK in pulmonary fibrosis and defective regulation of efferocytosis function as a result of that elevation, suggesting that targeting MERTK in macrophages may help to attenuate pulmonary fibrosis." (PMID 37120511, 2023). "Here, we found elevated MERTK expression in lung macrophages from IPF patients and mice with bleomycin-induced pulmonary fibrosis." (PMID 37120511, 2023). "Here, we show that MERTK expression is increased in lung macrophages from IPF patients and bleomycin-induced pulmonary fibrosis mice compared with controls." (PMID 37120511, 2023). "Moreover, our study reveals a previously unrecognized profibrotic effect of elevated macrophage MERTK in pulmonary fibrosis and defective regulation of efferocytosis function as a result of that elevation, suggesting that targeting MERTK in macrophages may help to attenuate pulmonary fibrosis." (PMID 37120511, 2023). "In summary, we found elevated MERTK expression in lung macrophages from IPF patients and mice with bleomycin-induced pulmonary fibrosis." (PMID 37120511, 2023). "However, the role of macrophage MERTK in efferocytosis and pulmonary fibrosis remains unknown." (PMID 37120511, 2023). "Serosa is also a key component of the human respiratory system and MerTK expression in serosa is much higher in the respiratory diseases of asthma, COPD, and respiratory distress syndrome, and lower in disease conditions such as allergic asthma and idiopathic pulmonary fibrosis." (PMID 38341954, 2024).
head and neck squamous cell carcinoma (7 papers, 2017 to 2024). A squamous cell carcinoma that arises from any of the following anatomic sites: lip and oral cavity, nasal cavity, paranasal sinuses, pharynx, larynx, and salivary glands. "We summarized existing RNA-seq data and showed that, compared with normal control, MerTK is highly expressed (24.2 %, p = 0.0003) in age related macular degeneration and highly expressed in head and neck squamous cell carcinoma (24.5 %, p < 0.0001), and periodontitis (8.4 %, p < 0.0001)." (PMID 38341954, 2024). "MERTK was recently found to be overexpressed in head and neck squamous cell carcinoma tumors (HNSCC), where its inhibition reduced the migratory potential of HNSSC cells." (PMID 28118606, 2017). "MERTK inhibition resulted in increased sensitivity of head and neck squamous cell carcinoma (HNSCC), triple-negative breast cancer (TNBC), and non-small-cell lung carcinoma (NSCLC) cell lines to AXL inhibition." (PMID 35626092, 2022). "Previous studies from our laboratory found that overexpression of MerTK activated P70S6K and C-RAF in head and neck squamous cell carcinoma (HNSCC) and TNBC cell lines." (PMID 38791148, 2024). "Out of these cell lines, two were selected as models in which to probe Tyro3 function; one of these was SCC-25 head and neck squamous cell carcinoma cells, which express both Axl and Tyro3 but not MerTK, whilst the other, MGH-U3 bladder carcinoma cells, expresses Tyro3 as a sole TAM receptor." (PMID 31766614, 2019).
non-alcoholic fatty liver disease (7 papers, 2015 to 2025). "It has been reported that AA genotype, which is associated with lower intrahepatic expression of MERTK, is protective against severe fibrosis also in Non-Alcoholic Fatty Liver Disease (NAFLD) through a mechanism involving the modulation of HCS activation." (PMID 36003399, 2022). "Similarly, this genotype is protective in non-alcoholic fatty liver disease (NAFLD): A/A homozygosity was associated to a lower rate of significant fibrosis and to a lower liver expression of MerTK." (PMID 31614787, 2019).